BDNF (brain derived neurotrophic factor)
Diseases named in the same sentence as BDNF in open-access papers (continued):
Sharing a sentence is not in itself a finding about the gene and the disease.
neuropathic pain (continued). "During pathogenesis of neuropathic pain, activated microglia produce and release a variety of pro-inflammatory cytokines (e.g., IL-1β, TNFα, IL-6, and CCL2) and BDNF to sensitize spinal neurons." (PMID 33739978, 2021). "SNL-induced neuropathic pain was also shown to be alleviated by the type-B monoamine oxidase (MAO-B) inhibitor, KDS2010, through competitively blocking the BDNF/trkB/NMDA-NR2B pathway, giving further support to the intervention of this pathway in the genesis of neuropathic pain." (PMID 38785946, 2024). "In another model of neuropathic pain, SNL, it was investigated whether BDNF controls the activation of GluN2B-NMDARs through Src homology-2 domain-containing protein tyrosine phosphatase-2 (SHP2) phosphorylation to produce pain." (PMID 38785946, 2024). "Removal of cell surface SORT1 by anti-SORT1 mAb may block BDNF signaling and anti-SORT1 mAb may be beneficial for the treatment of neuropathic pain, a major clinical challenge resulting from peripheral nerve trauma or disease." (PMID 33384578, 2020). "The upregulated expression of BDNF was detected in the spinal cord on day 21 after SNI in the present study, consistent with the previous reports, and further indicated that BDNF was highly involved in neuropathic pain." (PMID 31182984, 2019). "Indeed, TNF and BDNF are upregulated and released by DRG neurons and glia in inflammatory and neuropathic pain models and are strongly pro-nociceptive." (PMID 24642266, 2014). "Consistent with a role for BDNF-induced neuroplasticity in mediating the antinociceptive effects of exercise, we show that the concentration of SP and CGRP is significantly lower in animals with neuropathic pain in the enriched vs. impoverished environment." (PMID 24025218, 2013). "In models of neuropathic pain, CSF1 increased excitatory input to excitatory neurons in a BDNF-dependent manner and concurrently reduced excitatory input to inhibitory neurons via a BDNF-independent mechanism, thereby shifting the excitatory/inhibitory balance." (PMID 41292555, 2025).
ovarian carcinoma (31 papers, 2012 to 2025). A malignant neoplasm originating from the surface ovarian epithelium. "CA19-9, CA125, NLR, PLR, BDNF, lymph node metastasis and the CV were all risk factors for ovarian cancer." (PMID 36120557, 2022). "The results of this study show that lymph node metastasis, CA19-9, CA125, NLR, PLR, BDNF and the CV are all risk factors for ovarian cancer." (PMID 36120557, 2022). "Based on this, this study will explore the correlation between the five biochemical markers of CA19-9, CA125, NLR, PLR, BDNF, and other factors and ovarian cancer, and explore the possibility of diagnostic value for ovarian cancer." (PMID 36120557, 2022). "Ovarian cancer cells express significantly higher levels of BDNF compared with normal ovarian epithelial cells, and high BDNF expression and tumor nerve counts are associated with decreased survival in ovarian cancer patients." (PMID 33322770, 2020). "A positive association between NE and BDNF was also observed in human ovarian carcinoma, further indicating that the NE-BDNF axis promotes tumors." (PMID 32477953, 2020). "CA19-9, CA125, NLR, PLR, BDNF and their CV were all risk factors for ovarian cancer." (PMID 36120557, 2022). "This study revealed that increased intratumoral nerve presence strongly correlates with elevated BDNF and norepinephrine levels, advanced tumor stage, and shorter OS in patients with ovarian cancer." (PMID 40359002, 2025). "As discussed in Part I, the authors identified IgA responses to BDNF and TSPAN7 autoantigens in ovarian cancer and found that recombinant BDNF and TSPAN7 IgA antibodies reduce xenograft tumor growth." (PMID 40356924, 2025). "Ovarian cancer cells overexpress TrkB, and BDNF/TrkB can promote the migration and invasion of ovarian cancer cells by affecting myelination during nerve regeneration." (PMID 36900158, 2023). "They identified two extracellular antigens, BDNF and TSPAN7, a secreted molecule associated with poor prognosis in ovarian carcinoma and a tetraspanin overexpressed in ovarian carcinoma, respectively." (PMID 37419983, 2023). "In summary, CA19-9, CA125, NLR, PLR, and BDNF were all highly expressed in ovarian cancer patients and were related to the occurrence of ovarian cancer." (PMID 36120557, 2022). "In this study, the average BDNF H-score of the patients in the ovarian cancer group were greater than 2 points, suggesting positive result, which was statistically different from the benign tumor group." (PMID 36120557, 2022). "Studies had shown that BDNF can be detected in serum by ELISA, which was a step further from applying BDNF to ovarian cancer screening." (PMID 36120557, 2022). "A previous study reported that EGF and BDNF promote metastasis and proliferation of ovarian cancer cells by transactivating TrkB and EGFR, respectively." (PMID 35898394, 2022). "Studies had shown that BDNF in follicular fluid stimulates fallopian tube epithelial cells that TrkB to promote their survival, migration, and attachment, leading to ovarian cancer." (PMID 36120557, 2022). "Activation of the BDNF/TrkB pathway induces ovarian cancer cell migration, invasion, angiogenesis, and anoikis resistance." (PMID 34307378, 2021). "Delphinidin has been found to inhibit SKOV3 ovarian cancer cell metastasis by blocking BDNF-mediated invasion and migration as well as the production of BDNF-mediated downstream factors, including MMP-2/-9." (PMID 34768930, 2021). "For example, NE can bind to ADRB3 expressed by ovarian cancer cells to produce BDNF, and then BDNF acts on TrkB receptors on host neurons to increase the innervation of the tumor." (PMID 34307378, 2021). "In SKOV3 ovarian cancer cells treated with BDNF, delphinidin reduced Akt activation and NF-κB nuclear translocation." (PMID 34768930, 2021). "We find that knockdown of SHMT1 results in reduced BDNF expression and increase in transcription factor activator protein-2α expression in ovarian cancer cells." (PMID 28288142, 2017).
ovarian carcinoma (continued). "In the present study, we demonstrated that miR‐101 can repress ovarian cancer cell migration and invasion by blocking BDNF/TrkB signaling, which is an important supplement to previous research." (PMID 28904856, 2017). "Previous studies have shown high levels of BDNF and its receptor tropomyosin-related kinase B (TrkB) in various cancer types, including carcinomas of the ovary, colon, rectum, liver, mammary, cervix, bladder, chorion and prostate." (PMID 23531103, 2013). "IgA produced by immortalized B cells reactive to the N-terminal domain of thrombospondin-1 (TSPN) and brain-derived neurotrophic factor (BDNF) recognizes antigens on ovarian cancer cell lines and more effectively inhibits the growth of autologous tumors in vivo compared to control IgA." (PMID 41357192, 2025). "It suggested that BDNF may become a biomarker for molecular diagnosis, targeted therapy, and prognostic evaluation of ovarian cancer." (PMID 36120557, 2022). "BDNF and TrkB are overexpressed in epithelial ovarian cancer tissues." (PMID 34307378, 2021). "In addition to NE, neurotrophic factors and their ligands, such as BDNF/TrkB, can induce escape from anoikis in ovarian cancer, cervical cancer, and endometrial cancer cells." (PMID 34307378, 2021). "Interestingly, NE dependent activation of Adrβ3 in ovarian cancer cells induces BDNF through cAMP/JNK activation." (PMID 32477953, 2020). "In particular brain-derived neurotrophic factor (BDNF) and transcription factor activator protein-2α might be of interest for additional studies as potential mediators of ovarian cancer-promoting function of SHMT1." (PMID 28288142, 2017). "Studies also found that BDNF/TrkB increased metastasis in many malignancies, such as pancreatic ductal carcinoma, prostate cancer, lung cancer, hepatocellular carcinoma, colorectal cancer, gastric cancer, choriocarcinoma, ovarian cancer, and multiple myeloma." (PMID 27752996, 2016). "Analogously, a recent in vivo work on ovarian cancer (OC) demonstrated that cancer cells stimulated by norepinephrine (released by sympathetic neurons) increase the expression of the brain-derived neurotrophic factor (BDNF), whose release fosters tumor innervation." (PMID 34503281, 2021). "This evidence indicates that BDNF/TRKB may contribute to ovarian cancer progression." (PMID 31608227, 2019). "In ovarian cancer cell lines, both EGF and BDNF can transactivate the receptors and activate Akt, a downstream target." (PMID 29581842, 2018). "However, the detection method of BDNF in this study makes the results of this study on BDNF not directly applicable to clinical screening for ovarian cancer." (PMID 36120557, 2022).
Sepsis (31 papers, 2012 to 2026). Sepsis is defined as life-threatening organ dysfunction caused by a dysregulated host response to infection. "We further demonstrated that, in CLP-induced sepsis, myocardial BDNF was reduced that was associated with impaired cardiac function, increased myocardium fibrosis, elevated cardiomyocyte apoptosis, reduced NO production, and increased oxidative stress." (PMID 28770018, 2017). "After adjusting for covariates, BDNF and the need for mechanical ventilation or sepsis were associated with mortality." (PMID 23245494, 2012). "After adjusting for covariates, BDNF levels, the need for mechanical ventilation, and sepsis were associated with mortality." (PMID 23245494, 2012). "Sepsis alone was also associated with reduced levels of these neurotrophins, although the magnitude of the effect varied depending on the specific neurotrophin and brain region, with greater reductions observed for BDNF and NGF." (PMID 42176200, 2026). "Besides, late inflammation was associated with lower levels of BDNF and worse cognitive performance 30 days after sepsis." (PMID 40697274, 2025). "MIR503HG relieved sepsis and reduced cardiac dysfunction and inflammatory response by regulating the miR-497-5p/BDNF axis." (PMID 42256530, 2026). "Increased levels of the excitatory neurotransmitter glutamate (Glu) and reduced BDNF were observed in the hippocampus of experimental sepsis mouse models." (PMID 40697274, 2025). "The results showed that LGG supplementation significantly mitigated the sepsis-decreased BDNF expression level and p-TrkB in the hippocampus of mice with sepsis, which is consistent with previous reports." (PMID 38827289, 2024). "Research has shown that sepsis animal models exhibit decreased BDNF levels in hippocampal tissue, leading to cognitive dysfunction and highlighting the significance of BDNF in SAE." (PMID 39027435, 2024). "Moreover, LGG supplementation significantly alleviated the decrease in hippocampal BDNF expression and p-TrkB phosphorylation levels caused by sepsis, preserving neuronal survival and mitigating the pathological changes within the hippocampus of mice with sepsis." (PMID 38827289, 2024). "In contrast, LGG-treated mice with sepsis partially recovered the reduced expression of BDNF and NeuN." (PMID 38827289, 2024). "The glutamate receptor-mediated CaMKII/CREB/BDNF/TrKB signaling pathway influenced the role of the HPC-mPFC pathway in sepsis-induced cognitive dysfunction." (PMID 37284451, 2023). "However, the role and underlying mechanism of BDNF in sepsis‐induced ALI remain unclear." (PMID 37909847, 2023). "C. butyricum supplementation has been found to restore the decreased brain BDNF levels after stress or sepsis." (PMID 35462923, 2022). "A previous study demonstrated that the BDNF levels of patients with SAE were higher than those of patients with sepsis alone." (PMID 35432460, 2022). "Due to its ability to increase neurogenesis and peripheral BDNF delivery in patients and then ameliorate cognitive impairment, those drugs were used in both malaria and sepsis." (PMID 35250433, 2021). "BDNF was expressed in primary cardiomyocytes, and its expression was significantly reduced after sepsis." (PMID 28770018, 2017). "Upregulation of eNOS and subsequent induction of NO represent a major mechanism where BDNF reduces oxidative stress and decreases myocardial apoptosis and eventually attenuates cardiac dysfunction and improves animal survival in sepsis." (PMID 28770018, 2017). "In addition, L. rhamnosus GG was shown to improve cognitive–behavioral deficits in a sepsis mouse model by regulating BDNF expression and p-TrkB levels." (PMID 40002326, 2025). "LGG’s preservation of BDNF expression level may contribute to the protection against neuronal death observed in the hippocampus of LGG-treated mice with sepsis." (PMID 38827289, 2024).
Sepsis (continued). "In addition, selective deletion of BDNF in the alveolar epithelial type I cells of mice and its effect on sepsis‐induced ALI need to be explored in further studies." (PMID 37909847, 2023). "Accordingly, we investigated the expression and role of BDNF in ALI induced by sepsis in mice." (PMID 37909847, 2023). "Overall, we hypothesize that BDNF expression increases in the lung tissues of septic mice as a compensatory mechanism to ameliorate sepsis‐induced ALI by inhibiting excessive alveolar epithelial cell autophagy." (PMID 37909847, 2023). "Reduced BDNF expression maintains the dysfunction of the CNS in patients with severe sepsis." (PMID 34354558, 2021). "In one previous study, the LPS-induced reduction in hippocampal BDNF could have deleterious effects on cognitive function after sepsis development." (PMID 29137271, 2017). "CLP-induced sepsis results in markedly impaired hippocampus-dependent cognitive deficits, accompanied by increased kynurenine levels, elevated kynurenine/tryptophan ratios, reduced tryptophan expression, and decreased brain-derived neurotrophic factor (BDNF) concentrations." (PMID 40697274, 2025). "Finally, questions remain as to whether there is a sex‐dependent difference in the role of BDNF in sepsis‐induced ALI." (PMID 37909847, 2023). "However, the role of BDNF in sepsis‐induced ALI needs to be explored further." (PMID 37909847, 2023). "Since BDNF is known to specifically impact hippocampal-dependent tasks, the different environmental condition-induced modulation of BDNF could help to influence cognitive function during sepsis development." (PMID 29137271, 2017). "Hippocampal neuron and BDNF expression were measured to assess neuronal injury and to determine whether supplementation with LGG ameliorates neuroinflammation and sepsis." (PMID 38827289, 2024). "In this fluid-resuscitated rat model of sepsis, we found evidence of increased inflammation, oxidative injury, and decreased BDNF levels in the hypothalamus and brainstem but not in the pre-frontal cortex, an area not directly involved in autonomic control." (PMID 27229490, 2017). "In rats with sepsis, a sharp decline in survival was observed after CLP, with significantly reduced cardiac BDNF expression, enhanced myocardial fibrosis, elevated oxidative stress, increased myocardial apoptosis, and decreased endothelial nitric oxide (NO) synthase (eNOS) and NO." (PMID 28770018, 2017). "BDNF supplementation restored eNOS and NO and attenuated cardiac dysfunction; all these were abolished by NOS inhibition, highlighting the importance of NO in BDNF cardioprotection in sepsis." (PMID 28770018, 2017). "Although the causal relationship was not established, it is possible that sepsis induced enhanced hippocampal inflammatory response, which subsequently downregulated CREB/BDNF signaling, synaptic protein loss and ultimately resulted in hippocampus-dependent cognitive impariments." (PMID 31354429, 2019). "Moreover, in our study, BDNF was given after the onset of CLP, whether or not pretreatment of BDNF also exerts cardioprotection in sepsis remains known, which needs for further investigation." (PMID 28770018, 2017). "Regarding neurotrophic factors, CMS reduced the levels of BDNF, NT-3, NT-4, and NGF in both the hippocampus and frontal cortex, regardless of prior sepsis exposure." (PMID 42176200, 2026).
status epilepticus (30 papers, 2010 to 2025). Status epilepticus is defined as a continuous seizure lasting more than 30 min, or two or more seizures without full recovery of consciousness between any of them. "Another study has revealed a significant elevation in the levels of miR-132 and BDNF transcripts in the hippocampal neurons culture model of status epilepticus produced by Mg(2+)-deficient medium." (PMID 35088379, 2022). "p75NTR levels are elevated after Status Epilepticus (SE) in animals and increased activation by proBDNF, like mature BDNF, increases susceptibility to seizures." (PMID 31455240, 2019). "Strong neuronal activation by pilocarpine-induced status epilepticus caused an increase in all hippocampal dendritic laminae of BDNF transcripts encoding exons 2, 4, and 6 and also of BDNF exons 3 and 9a in DG molecular layer, whereas the other transcripts were restricted to the soma." (PMID 24198753, 2013). "The upregulation of BDNF by antioxidants had a neuroprotective potential in a rat model of status epilepticus, and BDNF upregulation counteracted cognitive deficits induced by ethanol in mice through the enhancement of hippocampal neurogenesis." (PMID 39942681, 2025). "Hippocampal BDNF levels are correlated with seizure severity and reduced by multisession ctDCS in status epilepticus animal models." (PMID 40193544, 2025). "One study examined the interplay between proBDNF and BDNF in neuronal apoptotic mechanisms during status epilepticus (SE) and concluded that BDNF was essential for promoting neuronal survival after SE, whereas proBDNF was linked to neuronal death." (PMID 40430064, 2025). "Specifically, the delivery of FGF-2 and BDNF in the rat hippocampus after pilocarpine-induced status epilepticus reduced various markers of inflammation including astrocytosis, microgliosis, and IL-1β expression." (PMID 38673746, 2024). "Frequent seizures, particularly status epilepticus, induce oxidative stress, alterations in growth factors like BDNF, and inflammation within the brain." (PMID 38732190, 2024). "Plasminogen proteolytic activity which is involved in the cleavage of pro-BDNF to BDNF is highly reduced following seizure and status epilepticus (SE)." (PMID 38006577, 2024). "And like KCC2, BDNF has been shown to downregulate NKCC1 expression in the hippocampus of rat status epilepticus models, likely through transcriptional mechanisms." (PMID 35458638, 2022). "Several studies have demonstrated that neurotrophic factors, including NGF and BDNF, are elevated after status epilepticus, which promotes the survival of neurons post-seizure." (PMID 33177978, 2020). "Under the experimental conditions employed in this study, pilocarpine leads to increased BDNF mRNA and protein levels peaking respectively 3 and 6 h after onset of status epilepticus." (PMID 26954758, 2016). "Intra-peritoneal injection of pilocarpine in rodents provokes generalized seizures leading to a status epilepticus (SE), which drives a massive increase in BDNF levels in the hippocampus." (PMID 26954758, 2016). "The results of dual luciferase assay and Western blotting showed that miR-155 antagonist exerted its action on status epilepticus by directly regulating the activity of BDNF." (PMID 27303295, 2016). "On one hand, consistent with the pro-epileptic effects of BDNF we observed an increased latency to onset of status epilepticus in BDNF-antisense-GFP-injected animals." (PMID 26954758, 2016). "Intrahippocampal overexpression of fibroblast growth factor 2 and brain-derived neurotrophic factor (BDNF) resulted in decreased neuronal cell death against pilocarpine-induced status epilepticus through enhanced neurogenesis and anti-inflammatory effects." (PMID 24287913, 2013). "Therefore, miR-132 has pro-epileptic effects via modulating BDNF/TrkB pathway in the hippocampal neuron culture model of status epilepticus." (PMID 35088379, 2022).